CLDN2 (claudin 2)
Diseases named in the same sentence as CLDN2 in open-access papers (continued):
Sharing a sentence is not in itself a finding about the gene and the disease.
lung adenocarcinoma (continued). "Claudin-2 (CLDN2), a tight junctional protein, is involved in the chemoresistance in a three-dimensional spheroid culture model of human lung adenocarcinoma A549 cells." (PMID 34205320, 2021). "In human lung adenocarcinoma A549 cells, MMP secretes epidermal growth factor, activates the EGFR-ERK signaling pathway, and promotes the expression of claudin-2, thus promoting tumor colonization (ciardiello and Tortora, 2008)." (PMID 34178945, 2021). "In conclusion, in human lung adenocarcinoma, the downregulation of CGN induces malignancy via the upregulation of MEK-dependent CLDN-2 and cell metabolism and cell migration, and the downregulation of FOXO1 induces malignancy via the downregulation of CGN and CLDN-4 and cell proliferation." (PMID 38338691, 2024). "Claudin-2 (CLDN2), a component of tight junction, is involved in the reduction of anticancer drug-induced toxicity in spheroids of A549 cells derived from human lung adenocarcinoma." (PMID 35886884, 2022). "CLDN2 that is not reported to contain putative NLS enhances proliferative behaviour in lung adenocarcinoma." (PMID 33386991, 2021). "In the case of claudin-2, its nuclear distribution is up-regulated by dephosphorylation and serves to retain ZONAB and cyclin D1 in the nucleus, resulting in the enhancement of proliferation of lung adenocarcinoma cells." (PMID 27641742, 2016). "Besides, CLDN2 retains its ability to complex with ZO-1, ZONAB, and cyclin D1, sequestering them in the nucleus, which results in enhanced cellular proliferation in lung adenocarcinoma." (PMID 36672179, 2023). "For instance, one of the most upregulated DEGs in LUAD of this study was CLDN2, which has been reported to be absent in normal lung epithelia, but highly expressed in human lung adenocarcinoma tissues and adenocarcinoma-derived cells including A549, RERF-LC-MS, and PC-3 cells." (PMID 33916417, 2021).
colon carcinoma (27 papers, 2010 to 2025). "In current studies, we have identified the role of class-II HDAC, HDAC-4 in regulating claudin-2 expression in causal association with differentiation in colon cancer cells." (PMID 29152115, 2017). "In current study, we provide data supporting causal significance of claudin-2 expression in regulating epithelial differentiation among colonocytes and colon cancer cells." (PMID 29152115, 2017). "We have documented similar association between HDAC-4 and claudin-2 expression in colon cancer cells undergoing spontaneous or HDACi-induced differentiation." (PMID 29152115, 2017). "Detailed differentiation analyses using colon cancer cells demonstrated inverse association between claudin-2 expression and epithelial differentiation." (PMID 29152115, 2017). "Increased CLDN2 expression is observed in colon tumors and is linked to tumor growth." (PMID 40687428, 2025). "have shown that Claudin-2 participates in the adhesion of colon cancer cells to hepatocytes and is highly expressed in VC." (PMID 38737903, 2024). "For example, claudin-2 is upregulated in colon cancer to promote tumour cell proliferation, and this upregulation depends on EGFR signalling and its downstream pathways." (PMID 36291586, 2022). "And recent evidence has indicated CLDN2 as an oncogene modulating colon cancer proliferation and migration/invasion via EGFR‐mediated signalling transactivation." (PMID 34965023, 2021). "Specifically, the interleukins have been shown to upregulate claudin-2 and downregulate ZO-1 in colonic cancer cell line T84 and airway epithelium, respectively." (PMID 32512917, 2020). "EGFR activation upregulated claudin-2 in colon cancer cells, and claudin-2 expression was decreased in the colon of waved-2 mice that have EGFR activation deficiency (see also Section 3.2 on the effects of EGFR on claudin-2)." (PMID 31726679, 2019). "Claudin-2 suppression in colon cancer cells has led to decreased cell proliferation through the modulation of EGF signaling." (PMID 31861759, 2019). "Accordingly, silencing claudin-2 in the colon cancer cell line Caco-2 and in tubular cells prevented EGF- and TNFα-induced increase in cell proliferation." (PMID 31726679, 2019). "In support of this notion, the claudin-2 promoter was affected in the opposite direction by EGF in Caco2 colon cancer and in MDCK tubular epithelial cells." (PMID 31726679, 2019). "Along the same lines miR-488 was shown to regulate invasion and lymph node metastasis in colon cancer cells through claudin-2-dependent control of the MAPK pathway." (PMID 31726679, 2019). "In additional studies, we identified specific role of the EGFR/ERK1/2 signaling in promoting claudin-2 expression in colon cancer cells." (PMID 29152115, 2017). "In conclusion, our findings identify claudin-2 as an important regulator of differentiation and growth properties of colonocytes and colon cancer cells." (PMID 29152115, 2017). "In present study, we report a key role of claudin-2 expression in regulating differentiation among colonocytes and colon cancer cells as claudin-2 expression antagonized epithelial differentiation." (PMID 29152115, 2017). "Overall, we here demonstrtae a role for HDAC-4 in regulating differentiation and growth properties of colon cancer cells in causal association with EGFR/ERK1/2-signaling and claudin-2 expression." (PMID 29152115, 2017). "Taken together, our data demonstrated role of the HDAC4/EGFR/ERK1/2 signaling in regulating claudin-2 expression in differentiating colon cancer cells." (PMID 29152115, 2017). "Accordingly, colon tumors demonstrated marked upregulation of the HDAC-4/ERK1/2/Claudin-2 signaling." (PMID 29152115, 2017). "Considering the pro-tumorigenic role of claudin-2 in colon cancer, we then determined clinical significance of our findings." (PMID 29152115, 2017).
colon carcinoma (continued). "Our demonstration of an important role for HDAC-4 and claudin-2 in colon cell growth would suggest that inhibitors of class-I and -II HDACs are likely to be more efficient at inhibiting colon cancer cell growth than class I-specific inhibitors." (PMID 29152115, 2017). "More recently, Claudin-2 has been identified as an important positive modulator of colon cancer tumorigenicity." (PMID 25823815, 2015). "Two other genes, TNS4 and CLDN2, which are known as clinical markers for colon cancer staging, also were upregulated in R cells." (PMID 24884630, 2014). "We have earlier shown disturbed protein expression of Beta-catenin, E-cadherin, occludin and claudin 2 compared to normal surrounding mucosa in colon carcinoma." (PMID 23675182, 2010). "In addition, claudin-1 and claudin-2 were up-regulated in IBD-associated dysplasia and sporadic adenomas, as well as in colon carcinomas and metastatic lesions, suggesting their involvement in tumorigenesis and the invasiveness of colonic epithelial cells." (PMID 36826032, 2023). "The upregulated level of CLDN2 increased the tumorigenicity of colon cancer cells." (PMID 37799140, 2023). "Claudin 2 overexpression in colon cancer cells also increases migration and invasiveness." (PMID 37239907, 2023). "Marked up-regulation of HDAC-4/ERK1/2/claudin-2 signalling has been demonstrated in colon cancer." (PMID 36291586, 2022). "Indeed, it has recently been shown that HDACs regulate the expression of Claudin-1 and Claudin-2 in colon cancer cells." (PMID 34830995, 2021). "Correspondingly, we found that colonic cancer cells responded to IL-4 and IL-13 stimulation with upregulation of CLDN2, significantly so in case of IL-4, while ACTA2 and TJP1 tended to be rather downregulated, significantly so in case of Caco-2 stimulation with IL-4." (PMID 32512917, 2020). "EGFR signaling is yet another key pathway linking colon cancer and claudin-2." (PMID 31726679, 2019). "Moreover, genetic alteration in claudin-2 expression was sufficient to modulate cyclin-D1 and P-21 expressions in colon cancer cells and modulate growth properties." (PMID 29152115, 2017). "Interestingly, in human patients affected with colon carcinoma, these genes (ALDH3A1, CLDN2 and CTEN) also have been associated with poor clinical outcomes." (PMID 24884630, 2014). "CMS4 was characterized by suppression of claudin 2, claudin 3, claudin 7, and occludin and upregulation of claudin 5 mRNAs, not aligning with any of the three TCGA genomic groups or with CMS2 despite the similarities in the prevalence of common colon cancer mutations." (PMID 37998722, 2023). "Similarly, claudin-2 is upregulated in colon cancer and is involved in cancer progression." (PMID 31861759, 2019). "Similarly, forced claudin-2 expression in colon cancer cells increases tumor growth in mice." (PMID 26061016, 2015). "Taken together, CLDN2‐mediated NDRG1 suppression modulates the expression of downstream EMT markers and CDKI genes to facilitate colon cancer progression." (PMID 34965023, 2021). "Interaction between claudin-2 and ZONAB was also demonstrated in colon cancer cells, where symplekin, a transcriptional regulator that cooperates with nuclear ZONAB, was shown to control claudin-2 levels." (PMID 31726679, 2019). "We have documented maximal claudin-2 and HDAC-4 expression in the proliferative compartment in mouse colonic epithelium and colon tumors in APCmin mice." (PMID 29152115, 2017). "The relation between the reduction of claudin-2 and the elevation of TER is suggested in human colon cancer Caco-2, HT-29, and T84 cells." (PMID 28939904, 2017). "have shown that the ability of colon cancer cells lacking Claudin-2 to metastasize to the liver decreases, and VC production decreases." (PMID 38737903, 2024). "In addition, claudin 2 interacts with ZO-1 and the transcription factor ZONAB/DbpA in colon cancer cells." (PMID 37239907, 2023).
colon carcinoma (continued). "Further, claudin-2 expression was a negative predictor for post-chemotherapy disease-free survival of colon cancer patients." (PMID 31726679, 2019).
ulcerative colitis (26 papers, 2015 to 2024). An inflammatory bowel disease involving the mucosal surface of the large intestine and rectum. "Significantly reduced expression of claudin-2 is reported to impair barrier functions and paracellular permeability in ulcerative colitis and Crohn’s disease." (PMID 39334888, 2024). "In this research, we assessed the utility of occludin, claudin-2, and zonulin measurements in evaluating the disease activity among patients with ulcerative colitis and Crohn’s disease." (PMID 39407507, 2024). "For example, in the colon of ulcerative colitis patients, the expression of channel-forming claudin-2 is often up-regulated, whereas other barrier-maintaining claudins show reduced expression levels, both contributing to a leak-flux type of diarrhea." (PMID 37999506, 2023). "In particular, pore-forming claudin-2 expression was upregulated in this disease, whereas claudin-4, 5, 7, and 8 were downregulated in crohn's disease (CD) and ulcerative colitis (UC)." (PMID 36597137, 2023). "Claudin-2 is often upregulated in individuals suffering from gastrointestinal diseases such as Crohn’s disease, ulcerative colitis, and HIV-enteropathy." (PMID 36014839, 2022). "The downregulations of several “tightening” TJ proteins like claudin-1 and -4, together with an upregulation of claudin-2, were found to contribute to the barrier defect observed in ulcerative colitis." (PMID 35734166, 2022). "It has been shown that both claudin-2 (CLDN-2) expression and IL-13 production appear to be higher in ulcerative colitis, in comparison to Crohn’s disease." (PMID 34768787, 2021). "Studies have shown that the expression of claudin-2 in the colon of patients with active ulcerative colitis is significantly increased." (PMID 32855360, 2020). "While claudin 2 is not expressed in normal colonic epithelium, previous authors have found claudin 2 expression in the diseased colons of patients with ulcerative colitis and Crohn’s disease." (PMID 30899070, 2019). "In a previous study of ulcerative colitis and Crohn’s disease biopsies, ZO-1 expression was reduced along with an up-regulation of another tight junction protein claudin-2." (PMID 30127744, 2018). "Increased expression of claudin-2 has been reported in the gut epithelia of patients with ulcerative colitis and Crohn’s disease." (PMID 28018313, 2016). "CLDN2 expression can be induced by TNFα and has been reported in various diseases, including Crohn’s disease, ulcerative colitis and celiac disease." (PMID 26589571, 2015). "A separate study demonstrated that miR-195-5p modulated the pathological effects of TNF-α in ulcerative colitis by reducing claudin-2 (CLDN2) expression, controlling the structure of the intestinal tight junctions and thereby reducing the permeability of the intestinal epithelial cells." (PMID 39125612, 2024). "Likewise, it is reported that patients with active Crohn's disease or ulcerative colitis and impaired intestinal permeability have decreased expression of occludin as well as claudin 4, 5, 7, and 8, whereas claudin 2 is strongly upregulated." (PMID 32793187, 2020). "Furthermore, in ulcerative colitis patients, the inflamed intestine had low VDR and increased Claudin-2." (PMID 36678175, 2023). "Using our validated assay, we have demonstrated that increased claudin-2 expression correlates with the severity of ulcerative colitis, where crypt destruction is not seen." (PMID 27598247, 2016). "In conclusion, our immunofluorescence and immunoblotting detection of claudins consistently demonstrates the suppression of claudin-1 and -4, the increase in claudin-2, and no change in the claudin-3 isoform in the present model of ulcerative colitis, all of which are reversed by nobiletin." (PMID 39334888, 2024).
lung carcinoma (23 papers, 2015 to 2025). "LC-MS/MS analysis in CD9 immunoprecipitates of crosslinker DTME-treated lung cancer cells identified direct interactions with claudin-1 although other claudins (claudin-2, −3, −4, −5, and −7) associated to a much lesser extent." (PMID 32091301, 2020). "However, nuclear translocation of Cldn2, another member of claudin family, has been implicated in lung cancer and associated with cell proliferation in lung epithelial cells." (PMID 27899769, 2016). "The bicellular tight junction molecule claudin-2 (CLDN-2) is extensively expressed in lung cancer tissues and promotes adenocarcinoma cell growth." (PMID 38001653, 2023). "CLDN-2, upregulated in lung cancer tissues, results in the proliferation of lung cancer cells, while the downregulation of angulin-1/LSR causes malignancy." (PMID 36297347, 2022). "SPIB was previously reported to potentiate early mesenchymal invasion and epithelial cell metastasis by repressing CLDN2 nuclear transcription in lung cancer." (PMID 34094897, 2021). "Experimental interventions that reduce claudin-2 expression in lung cancer cells reduce proliferation (see Section 5.1)." (PMID 31726679, 2019). "Consistently, we found that the expression of both CLDN2 and 3 were downregulated in human and murine lung cancer cells expressing Snail." (PMID 30190790, 2018). "We suggest that quercetin prevents tumorigenesis in human lung cancer partially mediated via the elevation of miR-16 and decrease in claudin-2 expression." (PMID 26061016, 2015). "Additionally, we also checked the other four scRNA-seq datasets about lung cancer or lung cells, and only limited number of cells showed high CLDN2 expressions." (PMID 37488117, 2023). "In lung cancer cells claudin-2 controls the G1/S transition through cyclin D1 and E1." (PMID 31726679, 2019). "However, it has been reported that nuclear-localized Claudin-2 mediates cell proliferation in lung carcinoma cells." (PMID 30692208, 2019). "Non-steroidal anti-inflammatory drugs (NSAIDs), that may provide protection against cancer, reduced both migration and claudin-2 expression in colon, stomach, and lung cancer cell lines." (PMID 31726679, 2019). "These cells were used in a series of studies to demonstrate that claudin-2 may be a therapeutic target in lung cancer." (PMID 31726679, 2019). "Similarly, knockdown of claudin-2 by siRNA in lung cancer cells A549 was recently reported to decrease proliferation concomitant with decreases in cyclin-D1 and E1 expression, cell cycle progression factors." (PMID 29152115, 2017). "It was reported that claudin-2 could form a complex with zonula occludens (ZO-1), ZO-1-associated protein (ZONAB), and cyclin D1 leading to enhancement of cell proliferation, which contributed to the development of lung cancer." (PMID 28383479, 2017). "In lung cancer, a comparison between adenocarcinoma and small-cell lung cancer (SCLC) revealed a significant difference only in CLDN-2 expression." (PMID 38338691, 2024). "For instance, epidermal growth factor (EGF)/epidermal growth factor receptor (EGFR) has been reported to be responsible for elevated claudin-2 expression in CRC and lung cancer." (PMID 28383479, 2017). "In our study, the expression of CLIC6, CLDN2, and BPIFB1 was significantly upregulated in H1975 and A549 cells, suggesting that high expression of these genes may influence the progression of lung cancer through immune regulation." (PMID 40399547, 2025). "Inhibited tumorigenesis in human lung cancer partially mediated via the elevation of miR-16 and decrease in claudin-2 expression without involving Akt and ERK1/2." (PMID 36926328, 2023). "Intriguingly, none of the other five independent lung or lung cancer scRNA-seq datasets showed high CLDN2+ AT2 signatures." (PMID 37488117, 2023).
lung carcinoma (continued). "There was no expression of claudin-2 in HCC827 lung cancer cells (data not shown)." (PMID 26081244, 2015). "Therefore, cdx2 should not be involved in the up-regulation of claudin-2 in lung cancer." (PMID 28608828, 2017).
Crohn disease (22 papers, 2011 to 2024). A gastrointestinal disorder characterized by chronic inflammation involving all layers of the intestinal wall, noncaseating granulomas affecting the intestinal wall and regional lymph nodes, and transmural fibrosis. "In Crohn’s disease, upregulation of claudin-1 and claudin-2 and decreased expression of intestinal epithelial isoforms claudin-3, -5, -8, and -12 were reported." (PMID 39334888, 2024). "In inflammation of the colon, such as Crohn’s disease, an increase in claudin-2 is considered to be a pathogenetic change in the state of the intestinal barrier." (PMID 38203449, 2023). "Disrupted expression and localization of tight junction components are observed in Crohn's disease and sepsis, with the upregulation of pore-forming claudin-2 and downregulation of sealing claudin-5 in both cases." (PMID 33579694, 2021). "In fact in IBD has been reported an upregulation of the pore-forming claudin-2 and down-regulation of occludin, particularly claudin-5 and -8 in Crohn's disease and claudin-4 and -7 in UC." (PMID 34589512, 2021). "Increased expression of claudin-2 determines an increased number of pores responsible for the paracellular movement of small molecules, characteristic of both UC and Crohn's disease." (PMID 34589512, 2021). "This is in line with earlier findings in MCDK-II cells, but also relates to intestinal diseases such as Crohn's disease and celiac disease showing increased CLDN2 protein levels." (PMID 29075202, 2017). "Claudin-2 is considered as a pore-forming tight junction protein that increases epithelial permeability in active Crohn's disease." (PMID 28002460, 2016). "In patients with Crohn’s disease, the expression of CLDN2 is dramatically up-regulated, especially in patients with low expression of the sealing tight junction protein CLDN8 (claudin 8)." (PMID 26589571, 2015). "Upregulation of pore-forming claudin 2 leads to altered tight junction structure and pronounced barrier dysfunction in mild to moderately active Crohn's disease." (PMID 21305056, 2011).